TNF (tumor necrosis factor)
Diseases named in the same sentence as TNF in open-access papers (continued):
Sharing a sentence is not in itself a finding about the gene and the disease.
disc degeneration (continued). "TNF-α, a potent proinflammatory cytokine, is responsible for the initiation and progression of disc degeneration by stimulating the NF-κB pathway, which promotes inflammation, ECM degradation, and apoptosis." (PMID 37790932, 2023). "When TNF-α is present in excessive amounts, as is often the case in pathological conditions like disc degeneration, it can lead to an increase in Bax and a decrease in Bcl-2, tipping the balance toward apoptosis." (PMID 37790932, 2023). "Another review on disc degenerative disease revealed that TNF-α inhibitors administered during surgery had been shown to stop macrophage infiltration." (PMID 37206531, 2023). "The isolated disc organ was cultured in medium, and the inflammatory cytokine TNF-α was used to induce disc degeneration." (PMID 36123708, 2022). "Interleukin 1β (IL1β) and tumor necrosis factor‐α (TNF‐α) are proinflammatory cytokines known to be key mediators in the development and progression of disc degeneration and low back pain." (PMID 35106811, 2022). "Our study found a statistically significant difference in serum TNF-α levels between the high-score group (total score > 18) and the low-score group (total score ≤ 18) for the total score of the lumbar disc degeneration scoring system." (PMID 35096205, 2022). "Inflammatory processes exacerbated by TNF‐α and/or IL1β are believed to trigger disc degeneration and, in later stages, low back pain." (PMID 35106811, 2022). "In particular, monoclonal antibodies (mAbs) against TNF‐α have shown promise for mitigating disc degeneration and relieving low back pain." (PMID 35106811, 2022). "TNFα-induced disc degeneration models have been widely utilized in previous studies; however studies presented limitations because of the severe toxicity of TNFα." (PMID 33441130, 2021). "Both ELISA and qRT-PCR analysis showed that the expression levels of inflammatory cytokines TNF-α, IL-1β, IL-6, and IL-17 were inhibited after overexpressing c-Jun in the disc degeneration rats." (PMID 34308759, 2021). "Studies have shown that the expression level of TNF-α is positively correlated with the degree of disc degeneration." (PMID 33936382, 2021). "Inflammatory processes exacerbated by several cytokines (i.e., TNF-α and IL-1β) are key mediators of disc degeneration and the resultant low back pain." (PMID 34616848, 2021). "Based on this, more and more studies have been devoted to blocking TNF-α mediated inflammatory response to delay disc degeneration and achieve positive therapeutic effects." (PMID 34504840, 2021). "FFD effectively protected against disc degeneration by antagonizing TNF-α-mediated destructive inflammation." (PMID 34504840, 2021). "These cases not only indicated the value of anti-LTα therapy in immunoinflammatory diseases but also provided new insights and inspiration for a combined anti-TNFα and anti-LTα treatment for degenerative disc diseases." (PMID 33441130, 2021). "Overall, FFD played an important role in the pathogenesis of disc degeneration by inhibiting cPLA2 activity against TNF-α." (PMID 34504840, 2021). "The NF-κB and Erk signaling pathways are key pathways that facilitates the function of TNF-α, and their role in disc degeneration has been extensively studied." (PMID 33936382, 2021). "It is accepted that TNF-α is elevated in the process of disc degeneration both systemically or locally." (PMID 34504840, 2021). "Anti-TNFα therapy is effective in treating many immunoinflammatory diseases, including degenerative disc diseases and RA." (PMID 33441130, 2021). "(a) FFD inhibited TNF-α-mediated extracellular matrix (ECM) degradation and (b) FFD rescued TNF-α induced inflammation in disc degeneration." (PMID 34504840, 2021). "MiR27a, which is up‐regulated by TNF‐α through the P38 pathway, blocks disc degeneration by targeting FSTL1 and can inhibit disc degeneration when expressed at high levels, thus providing a new potential therapeutic target for future treatment." (PMID 34190406, 2021).
disc degeneration (continued). "Meanwhile, other researchers have identified that the levels of IL-1β, IL-6, IL-17, and TNF-α have a positive relationship with the degree of disc degeneration." (PMID 34308759, 2021). "So far, it is widely accepted that TNF‐α contributes to disc degeneration by decreasing the anabolism and increasing the catabolism of ECM." (PMID 33015577, 2020). "Using these discs, an in vitro disc degeneration model was developed by the intervention of IL‐1β and TNF‐α as described." (PMID 32583517, 2020). "Multiple reports show that inflammatory cytokines such as IL‐1ß, IL‐6 and TNF‐α initiate the cascade that culminates in disc degeneration." (PMID 30900385, 2019). "Our present results showed that the expression of TNF-α, IL-1β and cleaved caspase 3 in degenerative disc disease (DDD) tissues are higher than those in lumbar vertebral fracture (LVF) tissues." (PMID 31518335, 2019). "TNFα is thought to play a major role in disc degeneration via recruitment of inflammatory cells to the IVD, destruction of extracellular matrix, and calcification and hyperalgesia associated with IVD disease." (PMID 30127455, 2018). "To explore the role of TNF-α and systemic inflammation in the pathogenesis of intervertebral disc disease, we used the Tg197 mouse, a well-established model of TNF-α-driven systemic inflammation." (PMID 30584238, 2018). "Anti-TNF-α therapies are currently being investigated for the treatment of disc degeneration, albeit with mixed results." (PMID 30584238, 2018). "Recent studies have shown early-onset disc degeneration in progranulin and IL-1ra knockout mice implying the importance of endogenous TNF-α and IL-1β inhibitors in the maintenance of disc health." (PMID 30584238, 2018). "This is the first study describing the constitutive presence of MUC1 in the human disc, and its increased expression during disc degeneration, and its in vitro downregulation during exposure to the proinflammatory cytokines IL-1ß and TNF-α." (PMID 28482827, 2017). "IL-1β has been shown to be upregulated in NP cells during disc degeneration in vivo and upregulated in response to LPS or TNF-α treatment in vitro." (PMID 24936787, 2014). "In contrast, induction of disc degeneration using IL-1β and TNF-α mimics the pathways that drive inflammatory processes and disease phenotype in humans." (PMID 24171898, 2013). "Recent studies on matrix synthesis and degradation in the disc have shown that proinflammatory cytokines, such as TNFα, are important cytokines involved in the pathogenesis of disc degeneration." (PMID 20003223, 2009). "Moreover, apigenin suppresses the expression of tumor necrosis factor-alpha (TNF-α)-mediated pro-inflammatory cytokines, thereby mitigating disc degeneration in rat models of IDD." (PMID 40786036, 2025). "The silencing of these gene would contribute to NFk-B activation by inducing the transcription of proinflammatory genes such as TNF-, IL-1, IL-6, and IL-8, as well as disc degeneration by upregulating the expression of matrix-degrading enzymes such as MMPs and ADAMTSs." (PMID 36768184, 2023). "TNFα and IL1β are the two inflammatory cytokines often used to recreate an inflammatory microenvironment in some in vitro models of tissue degeneration, including OA and disc degeneration." (PMID 37958603, 2023). "In a porcine model, lumbar discs treated with exogenous TNF-α displayed degenerative alterations, including annular fissures, loss of NP matrix, vascularization, and expression of IL-1β in the outer annulus, indicating that TNF-α is a driver of disc degeneration." (PMID 37101594, 2023). "Thus, TNF-α regulation of the Notch pathway has been shown to play a major role in cellular growth and differentiation in disc degeneration." (PMID 37206531, 2023). "Moreover, it had been reported that TNF-α was involved in the nerve irritation and ingrowth, inducing disc degeneration and increasing the painful behavior in an animal model." (PMID 35915608, 2022).
disc degeneration (continued). "It was shown that disc degeneration could produce a large number of inflammatory factors, such as TNF-α and IL-1β." (PMID 35855812, 2022). "On the other hand, extracellular matrix catabolic products produced during disc degeneration may promote macrophage-mediated IL-1β and tumor necrosis factor α (TNF-α) production through activation of NF-κB/IκBα complexes." (PMID 35333664, 2022). "In addition, as reported, intradiscal injection with the TNF-α reagent was considered to be a practicable way to construct a disc degeneration animal model." (PMID 35915608, 2022). "FFD effectively inhibited TNF-α/NF-κB signaling in the process of disc degeneration." (PMID 34504840, 2021). "Moreover, the expression of TNF-α and IL-1β increases with aging and degree of disc degeneration in degenerative human discs and animal discs." (PMID 34616848, 2021). "The toxicity of LTα is much lower than that of TNFα, indicating that LTα may have a potential value in the development of disc degeneration models." (PMID 33441130, 2021). "Above all, FFD rescued TNF-α-induced matrix destruction in disc degeneration." (PMID 34504840, 2021). "Furthermore, to investigate the optimum concentration of FFD in disc degeneration, primary mouse discs were cultured with TNF-α with a concentration of 10 ng/ml in the presence of FFD with various concentrations." (PMID 34504840, 2021). "To determine whether FFD inhibits TNF-α-mediated disc degeneration, we took advantage of mouse disc by ex vito culture." (PMID 34504840, 2021). "Chen proposed that interleukin-21 played a role in the pathological process of disc degeneration and could aggravate disc degeneration by stimulating TNF-α through the JAK/STAT pathway." (PMID 32111963, 2020). "Therefore, in vitro and ex vivo IVD inflammatory culture systems induced by TNF‐α are clinically relevant models for drug development for treatment of disc degeneration." (PMID 33015577, 2020). "Analysis using protein‐protein interaction (PPI) network and KEGG suggested that ITCH was not only at the core of gene interaction network, but also significantly enriched in the TNF signalling pathway, which has been proposed to be involved in the inter‐vertebral disc disease (IVDD) regulation." (PMID 32845084, 2020). "Furthermore, anticatabolic therapy in conjunction with TNF‐α inhibition would be required to slow down the pathologic cascade of disc degeneration." (PMID 33015577, 2020). "Therefore, in vitro and ex vivo inflammatory models utilizing TNF‐α provide relevant experimental conditions for drug development in disc degeneration research." (PMID 33015577, 2020). "Furthermore, they showed differences in overexpression of selective inflammatory and catabolic proteins (p<0.0001) similar to those found in human NP cells of different disc degeneration grades, such as IL-1β, TNF-α, ADAMTS-4, ADAMTS-5 and MMP-3." (PMID 31751427, 2019). "It is interesting to note that SM/J mice, a recently reported model of early onset spontaneous disc degeneration, are characterized by reduced systemic TNF-α levels when compared with C57BL/6 mice, suggesting a disconnect between TNF-α levels and extent of disc degeneration." (PMID 30584238, 2018). "Additionally, elevated levels of TNF-α in individuals with high body mass index correlates with both disc degeneration and LBP28." (PMID 30584238, 2018). "Collectively, Atsttrin is therapeutic in the intervertebral disc degenerative disease via targeting TNF-α and Atsttrin could be a noval drug candidate for the inflammatory degenerative diseases." (PMID 29312639, 2017). "It was also found that activation of the TNF signaling pathway can induce the secretion of proteinases by disc cells, which may contribute to protein aggregation and tissue degradation, thus playing a role in the progression of disc degeneration." (PMID 39430414, 2024). "Thus, TNF-α has been shown to play a major role in disc degeneration-related neuropathic pain." (PMID 37206531, 2023).
disc degeneration (continued). "IL-9 was shown to upregulate TNF-α and PGE2 production in NP cells, and its blood levels were positively associated with the degree of disc degeneration in IDD patients." (PMID 37101594, 2023). "As NP is an avascular, non‐innervated, and immune silent tissue, the high enrichment of genes related to axon guidance, angiogenesis, and TNF production indicated that Cluster 3 might be the “chief culprit” for the onset of disc degeneration and the inflammatory cascade." (PMID 35195356, 2022). "Moreover, exogenous TNF-α intradiscal injection can lead to disc degeneration in a porcine model." (PMID 35342351, 2022). "Previous and present studies have indicated that FFD could inhibit TNF-α-induced disc degeneration." (PMID 34504840, 2021). "This study sheds a new light that resveratrol can suppress TNF-α-induced disc AF cell apoptosis through regulating oxidative stress reaction and provides that resveratrol may be a potential drug to retard progression of disc degeneration." (PMID 34616848, 2021). "Therefore, the FDA-approved FFD may not only be a potential candidate for treating disc degeneration, but also provide an alternative for other TNF-α related diseases." (PMID 34504840, 2021). "Indeed, in disc degeneration models using in vitro three-dimensional cultures, human annulus cells display increased expression of pro-inflammatory cytokines, such as IL-1β and TNF-α, while exposure to TNF-α and IL-1β resulted in significant downregulation of GDF-5." (PMID 32443833, 2020). "The results of these studies suggest that Panax notoginseng might be useful for inhibiting the production of TNF-α, MMP-13, IL-1β and NO, which are associated with disc degeneration, and these effects could have caused the positive changes in disc height observed in this study." (PMID 23419188, 2013). "There is certain evidence in the literature that in a subgroup of patients, painful disc degeneration is characterized by increased levels of proinflammatory cytokines, e.g. interleukin 1β (IL-1β), interleukin 6 (IL-6), interleukin 8 (IL-8) and tumor necrosis factor α (TNF-α)." (PMID 22909087, 2012). "Thus, TNF-α up-regulation in this model may indicate TNF-α contribution to the pathogenesis of disc degeneration." (PMID 22394620, 2012). "Biochemical analysis showed that IL-6 and TNF-α levels were within normal ranges in the groups treated with PRP and PRP + ropivacaine, whereas these levels remained elevated in the untreated disc degeneration groups, indicating ongoing effects of degeneration." (PMID 40606908, 2025). "In rat LSI-induced disc degeneration models, AMD preserved type II collagen and proteoglycan content while reducing TNF-α and IL-6 secretion." (PMID 40868398, 2025). "IL-6, IL-1β and TNF-α show high levels in LDH, and their expression levels are affected by age and the degree of disc degeneration." (PMID 38268042, 2024). "On the contrary, we recorded significantly increased endogenous expression levels of inflammatory cytokines and their receptors such as IL-1β/IL-1 R and TNF-α/TNF-α R1, where their levels increased with severity of disc degeneration." (PMID 39286594, 2024). "Our findings revealed that digoxin treatment inhibited the upregulation of MMP-13 and ADAMTS4/5 induced by TNF-α, leading to restoration of the expression of Col-2 and Aggrecan, indicating its potential role in inhibiting ECM degradation in disc degeneration." (PMID 37790932, 2023). "This study further supports that the TNF‐α cytokine is a potent mediator of inflammatory response in the IVD, particularly in NPCs, and leads to disc degeneration through increased catabolism due to ECM degradation." (PMID 35106811, 2022). "Based on the important role of TNF-α in IVD degeneration and the anti-inflammatory effect of FFD in previous studies, the present study determined the role of FFD in disc degeneration." (PMID 34504840, 2021).
disc degeneration (continued). "In the present study, we sought to establish TNF‐α induced in vitro and ex vivo IVD inflammation models, which would represent preclinical testing systems for screening of anti‐inflammatory drugs for disc degeneration treatment." (PMID 33015577, 2020). "In disc degeneration, AKT is phosphorylated, and activated in NPCs, which was realized by the several inflammatory responses, including IL-1β, IL-6, and TNFα." (PMID 32526705, 2020). "During disc degeneration, it has been demonstrated that IVD cells secrete proinflammatory cytokines such as TNF‐α, IL‐1α, IL‐1β, IL‐6, and IL‐17." (PMID 31463438, 2018). "Intervertebral disc degeneration (IDD) is involved in inflammation in which TNF-α plays a key role." (PMID 29312639, 2017). "The results of this study indicated that abnormal expression of IAPP in the NP cellstriggers secretion of IL-1 and TNF-α, which act as pro-inflammatory cytokines that regulate MMP expression and accelerate disc degeneration." (PMID 28149534, 2017). "Immunohistochemistry staining demonstrated that the levels of TNF-α, IL-1β and MMP-13 were increased in the pathogenesis of intervertebral disc disease." (PMID 28498809, 2017). "TNF-α and IL-1β exacerbate LDH inflammatory processes, and are believed to be key players during disc degeneration." (PMID 28498809, 2017). "Our results showed that vitamin E also attenuated the ROS-mediated or TNFα-mediated catabolic effect in the cultured AF cells, which indicated that vitamin E as well as NAC has the potential for preventing disc degeneration." (PMID 26542776, 2015). "The PI3K/Akt signaling pathway is activated by TNF-α in NP cells, and treatment with the PI3K inhibitor LY294002 showed protective effects against TNF-α-induced premature senescence, suggesting its role in mediating activation of CS and disc degeneration." (PMID 37189433, 2023). "Our work provides that baicalein attenuates TNF-α-activated apoptosis in human NP cells through promoting the PI3K/Akt pathway, indicating that baicalein is a new potential candidate for clinical therapy to attenuate disc degeneration." (PMID 37041597, 2023). "Taken together, TNF‐α is an essential initiator of the proinflammatory environment in IVD tissue and cells that leads to the tissue ECM degradation and disorganization, and, therefore, to disc degeneration and back pain." (PMID 35106811, 2022). "Since TNF-α mainly exhibited its inflammatory catabolic effect through TNFR1, herein, we compared FFD with TNFR1 inhibitor for the efficacy of blocking the TNF-α effects on disc degeneration." (PMID 34504840, 2021). "Taking into account the importance of TNF-α in the inflammatory process in disc degeneration, we next investigated whether FFD exhibits its role by antagonizing TNF-α’s role." (PMID 34504840, 2021). "Inflammation in the IVD can be characterized by an increased expression of pro-inflammatory molecules such as interleukin (IL)-6, IL-1β, and tumor necrosis factor alpha (TNF-α), and contributes to the development of degenerative disc disease (DDD) and low back pain (LBP)." (PMID 32714187, 2020). "Injecting TNFα into the lumbar IVD induces pain behavior and disc degeneration in rats." (PMID 32613168, 2020). "This nontraumatic model of disc degeneration, based on the use of inflammatory cytokines IL-1β and TNF-α, mimics known gene expression patterns observed in the degenerative human disc." (PMID 24171898, 2013). "Importantly IL‐1β and TNFα, regarded as key contributors to disc degeneration, were not shown to affect the NP cell differentiation of mesenchymal stem cells (MSCs) in the NPgel." (PMID 31463465, 2019). "Hence, it is possible that genetic variation in the promoter region of TNF-α (-308G/A) could play a significant role in disc degeneration, but there is a lack of sufficient evidence to support the mechanism of pathogenesis, especially in CCS." (PMID 37371064, 2023).